PPP1R3G (protein phosphatase 1 regulatory subunit 3G)
Description:
Glycogen-targeting subunit for protein phosphatase 1 (PP1). Involved in the regulation of hepatic glycogenesis in a manner coupled to the fasting-feeding cycle and distinct from other glycogen-targeting subunits (By similarity).
Tractability: No criterion of Open Targets' tractability assessment is met for any kind of drug.
Gene: Protein-coding gene on chromosome 6 (5,085,341 to 5,089,487, forward strand). Ensembl gene ENSG00000219607.
Gene Ontology:
Molecular function: protein binding; glycogen binding; protein phosphatase 1 binding; protein phosphatase binding
Biological process: regulation of glycogen biosynthetic process
Cellular component: protein phosphatase type 1 complex; cytoplasm
Genetic constraint (gnomAD): Loss-of-function variants: 4 observed, 2.99 expected, observed/expected ratio (o/e) 1.34, 90% interval 0.6 to 1.91. That is too few expected variants to judge how well the gene tolerates losing a copy. Missense variants: 399 observed, 305.35 expected, observed/expected ratio (o/e) 1.31, 90% interval 1.2 to 1.42. Synonymous variants: 185 observed, 146.62 expected, observed/expected ratio (o/e) 1.26, 90% interval 1.12 to 1.42.
Homologues: Orthologues: chimpanzee PPP1R3G (98% identical), macaque PPP1R3G (91% identical), pig PPP1R3G (75% identical), rat Ppp1r3g (68% identical), mouse Ppp1r3g (66% identical), zebrafish PPP1R3G (25% identical), Caenorhabditis elegans H18N23.2 (16% identical), Drosophila melanogaster Gbs-70E (15% identical). Paralogues in human: PPP1R3D (27% identical), PPP1R3E (24% identical), PPP1R3A (20% identical), PPP1R3F (19% identical), PPP1R3B (17% identical), PPP1R3C (17% identical).
Diseases named in the same sentence as PPP1R3G in open-access papers:
PPP1R3G is named in the same sentence as 10 diseases in open-access papers, as found by Europe PMC text mining. Sharing a sentence is not in itself a finding about the gene and the disease. The quoted sentences say what the papers report.
Insulin resistance (3 papers, 2022 to 2024). Increased resistance towards insulin, that is, diminished effectiveness of insulin in reducing blood glucose levels. "Among the downregulated genes, Ppp1r3g, which has a role in controlling glycogen synthesis, and Igfbp2, which functions in insulin resistance, were markedly reduced." (PMID 38619504, 2024). "The DEGs and DELs between the QGL and MOD groups, such as TG, SIK1, PPP1R3C, CRTC2, PGC-1α, G6PC, PPP1R3G, and SREBP1 were found to be relevant to insulin resistance." (PMID 36452137, 2022). "Our research indicated that QGD may improve insulin resistance via regulating the expression of CRTC2, SIK1, PPP1R3C, PGC-1α, G6PC, PPP1R3G, and SREBP1, which are involved in gluconeogenesis." (PMID 36452137, 2022).
lung adenocarcinoma (3 papers, 2021 to 2025). A carcinoma that arises from the lung and is characterized by the presence of malignant glandular epithelial cells. "This analysis revealed that the protein levels of both LYPD3 and PPP1R3G were significantly elevated in lung adenocarcinoma tissues compared to matched normal adjacent tissues (p < 0.05 for both; Reference to the supplementary S1A,B)." (PMID 41358202, 2025). "Finally, we used quantitative PCR to verify the expression level of PPP1R3G in normal tissues and lung adenocarcinoma tissues of mice." (PMID 34592886, 2021). "Univariate Cox regression analysis suggested that the high expression levels of up-regulated DEGs including APOL1, ETFB, KLK8, PPP1R3G, PRL, and SPTA1 were significantly correlated with poorer overall survival (OS) in lung adenocarcinoma." (PMID 38183079, 2024). "The protein phosphatase 1 regulatory subunit 3 G (PPP1R3G) participates in many tumor biological processes; however, its effects on lung adenocarcinoma (LUAD) have not been clarified." (PMID 34592886, 2021).
lung carcinoma (2 papers, 2021 to 2025). "Next, we explored the association of PPP1R3G with clinicopathological features of individuals with LUAD in the TCGA data resource to elucidate possible functions of PPP1R3G in lung cancer." (PMID 34592886, 2021). "This analysis led to the discovery of a 3-gene signature—comprising PPP1R3G, CREG2, and LYPD3—that is characteristic of the resistant lung cancer cells." (PMID 41358202, 2025).
Hepatic steatosis (1 paper, 2025). Steatosis is a term used to denote lipid accumulation within hepatocytes. "Overexpression of protein phosphatase 1 regulatory subunit 3g (Ppp1r3g) in hepatocytes increases hepatic glycogen accumulation, reduces hepatic steatosis, and mitigates alcohol-induced liver injury, suggesting a functional relationship between glycogen metabolism and ALD pathology." (PMID 41465598, 2025).
steatosis (1 paper, 2025). Increased lipid within the cytoplasm of cells. "Previous studies showed that hepatocyte-specific overexpression of Ppp1r3g restored glycogen accumulation and attenuated ethanol-induced liver injury and steatosis." (PMID 41465598, 2025).
systemic inflammatory response syndrome (1 paper, 2021). SIRS is a serious condition related to systemic inflammation, organ dysfunction, and organ failure. "Finally, Ppp1r3g−/− mice are protected from tumor necrosis factor-induced systemic inflammatory response syndrome, confirming the important role of PPP1R3G in regulating apoptosis and necroptosis in vivo." (PMID 34862394, 2021).
cancer (3 papers, 2021 to 2024). A tumor composed of atypical neoplastic, often pleomorphic cells that invade other tissues. "Our data revealed that the expression pattern of PPP1R3G varies across different types of cancer." (PMID 38402263, 2024).
tumor (1 paper, 2021). "We analyze the correlation between PPP1R3G gene somatic copy number alterations and tumor infiltration levels by SCNA module in LUAD." (PMID 34592886, 2021). "We further compared the tumor infiltration levels in LUAD with different somatic copy number alterations in PPP1R3G." (PMID 34592886, 2021). "Herein, This study aimed to investigate the prognostic value of PPP1R3G and its relationship with tumor immune cell infiltration in LUAD." (PMID 34592886, 2021). "We demonstrate for the first time that PPP1R3G significantly affects the prognosis of LUAD patients and is associated with tumor immune cell infiltration." (PMID 34592886, 2021). "Further, Due to the database, we were unable to further explore the relationship between PPP1R3G and tumor immunocytes." (PMID 34592886, 2021). "PPP1R3G might be a poor prognostic biomarker for LUAD and is associated with tumor immune cell infiltration." (PMID 34592886, 2021). "Overall, PPP1R3G might be a poor prognostic biomarker for LUAD and is associated with tumor immune cell infiltration." (PMID 34592886, 2021). "Data from the TCGA were employed to investigate the differences in PPP1R3G expression between nonmalignant and tumor tissues." (PMID 34592886, 2021). "The expression of PPP1R3G mRNA in nonmalignant tissues (59 samples) and LUAD tumor tissues (515 samples) were analyzed according to the TCGA database." (PMID 34592886, 2021).
PPP1R3G also shares sentences with these, for which no sentence is quoted: hyperhomocysteinemia (1 paper); small cell lung carcinoma (1).